TMPRSS5 (transmembrane serine protease 5)
Description:
May play a role in hearing.
Synonyms: MGC141886; MGC148044; SPINESIN
Tractability: Antibody: UniProt places it where antibodies can reach, with high confidence; its Gene Ontology location is reachable by antibodies, with high confidence; UniProt predicts a signal peptide or a membrane-spanning region.
Gene: Protein-coding gene on chromosome 11 (113,687,543 to 113,706,382, reverse strand). Ensembl gene ENSG00000166682.
Subcellular location: Cell membrane
Subcellular location (Human Protein Atlas): Nucleoplasm
Gene Ontology:
Molecular function: peptidase activity; serine-type peptidase activity; serine-type endopeptidase activity
Biological process: proteolysis; protein processing
Cellular component: plasma membrane; membrane
Genetic constraint (gnomAD): Loss-of-function variants: 46 observed, 44.6 expected, observed/expected ratio (o/e) 1.03, 90% interval 0.81 to 1.32. The upper end of that interval is the gene's LOEUF score, 1.32, which puts it in group 5 of 6, group 1 being the genes least tolerant of losing a copy. Missense variants: 580 observed, 495.23 expected, observed/expected ratio (o/e) 1.17, 90% interval 1.09 to 1.25. Synonymous variants: 225 observed, 188.9 expected, observed/expected ratio (o/e) 1.19, 90% interval 1.07 to 1.33.
Homologues: Orthologues: chimpanzee TMPRSS5 (97% identical), macaque TMPRSS5 (91% identical), dog TMPRSS5 (82% identical), rat Tmprss5 (80% identical), mouse Tmprss5 (78% identical), rabbit TMPRSS5 (62% identical), zebrafish tmprss5 (45% identical), tropical clawed frog tmprss5 (36% identical), Drosophila melanogaster Sb (25% identical), Drosophila melanogaster CG17242 (12% identical). Paralogues in human: TMPRSS6 (30% identical), ST14 (29% identical), TMPRSS13 (28% identical), TMPRSS9 (28% identical), TMPRSS3 (27% identical), TMPRSS7 (27% identical), TMPRSS15 (26% identical), TMPRSS2 (26% identical), HPN (26% identical), TMPRSS11E (23% identical), TMPRSS11D (22% identical), TMPRSS11F (21% identical), and 5 more.
Diseases named in the same sentence as TMPRSS5 in open-access papers:
TMPRSS5 is named in the same sentence as 18 diseases in open-access papers, as found by Europe PMC text mining. Sharing a sentence is not in itself a finding about the gene and the disease. The quoted sentences say what the papers report.
ischaemic stroke (2 papers, 2022 to 2024). "TFPI, CD40, IL6RA and MMP12 were associated with a lower risk of any stroke and any ischaemic stroke, while TMPRSS5 and CD6 was associated with a higher risk of any stroke." (PMID 36253349, 2022). "Similarly, CD6 pQTLs colocalized with any stroke genetic associations; CD40 pQTLs colocalized with the genetic associations for any stroke, any ischaemic stroke and large artery stroke; TMPRSS5 pQTLs colocalized with any stroke, any ischaemic stroke and cardioembolic stroke genetic associations." (PMID 36253349, 2022). "These analyses revealed that atrial fibrillation may mediate a quarter of the association of TMPRSS5 and IL6RA with ischemic stroke." (PMID 39628323, 2024). "We were unable to find other studies that implicate TMPRSS5 in cardiovascular disease, both for any ischaemic stroke and cardioembolic stroke, an effect that might be mediated by the risk of atrial fibrillation." (PMID 36253349, 2022).
atrial fibrillation (1 paper, 2022). A disorder characterized by an electrocardiographic finding of a supraventricular arrhythmia characterized by the replacement of consistent P waves by rapid oscillations or fibrillatory waves that vary in size, shape and timing and are accompanied by an irregular ventricular response. "Body mass index, white matter hyperintensity and atrial fibrillation appear to mediate the TFPI, IL6RA, TMPRSS5 associations with stroke." (PMID 36253349, 2022). "Taken together, TMPRSS5 represents a potentially promising therapeutic target for atrial fibrillation and cardioembolic stroke, and further research is warranted to decipher the mechanism through which it protects against cardiovascular and neurological diseases." (PMID 36253349, 2022).
cardioembolic stroke (1 paper, 2022). "Genetically higher levels of plasma TMPRSS5 were associated with a higher risk of cardioembolic stroke, as well as protein−calorie malnutrition (metabolic trait)." (PMID 36253349, 2022). "For instance, we found that TMPRSS5 was a potential novel drug target for cardioembolic stroke, while other proteins in the Type II transmembrane serine protease family (TTSPs) that play crucial roles in cardiac functions could not be evaluated." (PMID 36253349, 2022).
deafness (1 paper, 2020). An inherited or acquired condition characterized by the complete loss of the ability to hear from one or both ears. "Mutations in TMPRSS5 have been associated with deafness, and other family members may play similar roles." (PMID 31833243, 2020).
neuropathy (1 paper, 2020). A disorder affecting the nervous system that manifests with pain, tingling, numbness, and/or muscle weakness. "TMPRSS5 was consistently elevated about twofold across all CMT1A patients but was not correlated to severity of neuropathy by CMTES‐R or CMTNS‐R, or to electrophysiological parameters CMAP and MNCV, or to age." (PMID 31833243, 2020).
Stroke (1 paper, 2022). Sudden impairment of blood flow to a part of the brain due to occlusion or rupture of an artery to the brain. "We found the associations of TFPI, IL6RA and TMPRSS5 with stroke were likely to be mediated by one or more of these risk factors." (PMID 36253349, 2022). "This analysis was restricted to three proteins, i.e. TFPI, TMPRSS5 and IL6RA, that showed evidence of an effect in both MRs with risk factors and stroke outcomes." (PMID 36253349, 2022). "The genetic associations with stroke colocalize (Posterior Probability >0.7) with the genetic associations of four proteins (TFPI, TMPRSS5, CD6, CD40)." (PMID 36253349, 2022). "The association of the genetic variants selected as instrumental variables for four proteins (TFPI, TMPRSS5, CD40 and CD6) colocalized with the stroke associations (posterior probability (PP) ≥0.7) i.e. the associations in these regions were likely due to the same underlying causal variants." (PMID 36253349, 2022). "We, therefore, focused further analyses on the proteins with cis-pQTLs only (i.e. TFPI, TMPRSS5, CD40, MMP12, IL6RA, CD6), as these associations with stroke are unlikely to be due to pleiotropy." (PMID 36253349, 2022).
cardiovascular disease (2 papers, 2020 to 2022). "We identified one known locus (ANGPTL4) and four new loci (PLCL1, RC3H2, TMPRSS5, and LDLRAD1) associated with cardiovascular disease risk that warrant further investigation." (PMID 33186364, 2020). "This study identified one known locus (ANGPTL4) and four new loci (PLCL1, RC3H2, TMPRSS5, and LDLRAD1) associated with cardiovascular disease risk that warrant further investigation." (PMID 33186364, 2020).
infection (1 paper, 2023). The state of being infected such as from the introduction of a foreign agent such as serum, vaccine, antigenic substance or organism. "Thus, we mapped the transmembrane serine proteases TMPRSS5 and SS15 as novel receptors taking part of the infection machinery." (PMID 36806094, 2023).
TMPRSS5 also shares sentences with these, for which no sentence is quoted: Age-related nuclear cataract (1 paper); Charcot-Marie-Tooth disease (1); Hypertension (1); large artery stroke (1); malnutrition (1); neurodegenerative disease (1); neurological diseases (1); Obesity (1); peripheral neuropathy (1); schizophrenia (1).